STAT3 (signal transducer and activator of transcription 3)
Diseases named in the same sentence as STAT3 in open-access papers (continued):
Sharing a sentence is not in itself a finding about the gene and the disease.
tumor (continued). "As one possibility, Cui and co-workers demonstrated that the Forkhead box M1 (FOXM1) transcription factor regulates c-MET expression via ERK, AKT and STAT3 pathways, creating a positive feedback loop that promotes tumor growth." (PMID 30567565, 2018). "For example, IL-6 binding to CD5+ B cells promoted tumor growth by activating STAT3 in mouse tumor models, and were observed to be correlated with phosphorylated STAT3 in multiple human tumors, including NSCLC50." (PMID 29844447, 2018). "Anti‐PD1 antibody led to a significant decrease in the number of OS lung metastases, enhanced tumor apoptosis, decreased tumor cell proliferation, and p‐STAT‐3/p‐Erk1/2 signaling blockade in OS lung tumors." (PMID 29733528, 2018). "A well-established driver of tumorigenesis in multiple solid tumors, STAT3 induces and maintains a pro-inflammatory environment during tumor initiation and progression, and is aberrantly activated in EOCs." (PMID 30127274, 2018). "They modulate various cell signaling pathways that are mediated by transcription factors, including NF-κB, signal transducer and activator of transcription 3 (STAT3), and HIF-1, which are linked to inflammation, tumor growth, invasion, and metastasis." (PMID 29954119, 2018). "As mentioned at the beginning, STAT3 is also important in tumor biology for its ability to promote cancer through regulating cancer stem cell activities." (PMID 29588647, 2018). "NF-κB-dependent IL-6 production and the downstream STAT3 signaling have been demonstrated to promote neoplastic cell proliferation and survival, as well as induce chemoresistance of diverse tumor cell lines in vitro." (PMID 30042442, 2018). "BI-ALCL tumor cells, like their systemic counterparts, show phospho-STAT3 (p-STAT3) nuclear staining, demonstrating the constitutive activation of STAT3 and its role in the oncogenesis." (PMID 29617304, 2018). "More recently, a role for STAT3, which was expressed in the epithelium, in promoting an immunosuppressive tumour microenvironment during the early stages of tumour initiation and progression has been demonstrated in a polyomavirus middle T mouse model." (PMID 29875329, 2018). "Using NIH3T3 fibroblasts with STAT3 constitutive activation, we further proved that Wwox ability to suppress in vivo tumor growth depends on STAT3 activation." (PMID 30154439, 2018). "Myeloid-derived suppressor cells, which are immature myeloid progenitor cells and the major immune suppressor cells, play important roles in tumor progression by activating transcription factors NF-κB and STAT-3 in the tumor inflammatory microenvironment." (PMID 29636841, 2018). "Taken together, our results demonstrate that the negative regulation of STAT3 activity by Hst imposed a tumor inhibition synergy with CPT-11 through recruitment of tumoricidal macrophages into the tumor microenvironment." (PMID 29963254, 2018). "Studies have also shown that the suppression of constitutively active STAT3 leads to growth inhibition and apoptosis in tumor cell lines as well as in xenograft models." (PMID 30577812, 2018). "Earlier studies have shown that STAT3 mediates tumor-promoting inflammation in part by inhibiting expression of activators of anti-tumor immunity." (PMID 30389925, 2018). "Male mice with deletion of epithelial Stat3 displayed elevated tumor burdens and Ki-67 immunoreactivity compared to male CC-LR animals." (PMID 30389925, 2018). "The overexpression of STAT3 has been observed among various types of cancers, with reports suggesting that overexpressed STAT3 promotes tumor genesis by protecting against cell apoptosis and enhancing angiogenesis, proliferation, invasion and metastasis." (PMID 30123088, 2018). "The suppression of STAT-3 pathway reduced tumor burden, suggesting the possibility of cancer therapy targeting senescence program of CAFs." (PMID 29360827, 2018). "Members of the let-7 miRNA family are also widely accepted to be tumour suppressors that indirectly regulate STAT3." (PMID 29875329, 2018).
tumor (continued). "Previous studies demonstrated that the overexpression and constitutive activation of STAT3 were involved in the oncogenesis of NPC cells, and treatment with STAT3 inhibitors suppressed the cell proliferation and tumor growth." (PMID 29738439, 2018). "IL-6 also supports tumor cell survival by inducing the expression of survivin through direct binding of STAT-3 to the survivin promoter." (PMID 29930760, 2018). "We showed that TFRG were able to downregulate the levels of iNOS via JAK2/STAT3 signal pathway which were highly expressed and activated in tumor tissues." (PMID 29951107, 2018). "We have reported that tocilizumab in combination with anti-RCC drugs can effectively suppress tumor growth in vitro and in vivo through repressing activation of STAT3, Akt and mTOR as well as expression of HIF or SOCS3." (PMID 30167088, 2018). "Curcumin can suppress STAT3 activation pathway and tumor growth in an orthotopic murine model of ovarian cancer." (PMID 30319623, 2018). "Several STAT3 target genes are reported to be upregulated during tumour formation including B-cell lymphoma-extra large (Bcl-XL), Survivin, Hsp70, CCND1, MYC, HIF, and VEGFA, where STAT3 orchestrates the angiogenic response through HIF and VEGFA." (PMID 29301334, 2018). "Normalisation of STAT3 levels in gp130F/F:Stat3± mice inhibited both tumour development and lymphoid neogenesis." (PMID 29417587, 2018). "In conclusion, we demonstrated that MSC-CM is a potent tumour suppressor of MDA-MB-231 cells by inhibiting Stat3 activation and down-regulating its downstream gene expression." (PMID 30297887, 2018). "Our results indicate for the first time that icariin inhibits both inducible and constitutive STAT3 activation, which makes it a potentially effective suppressor of tumor cell survival, proliferation and angiogenesis." (PMID 29899697, 2018). "STAT3 activity promotes the production of immunosuppressive factors that activate STAT3 in diverse immune-cell subsets, altering gene-expression programs and, thereby, restraining anti-tumor immune responses." (PMID 29963254, 2018). "Multiple studies have shown that the IL-11/IL-11R/STAT3/NF-κB signaling axis plays important roles in tumor growth, angiogenesis, and metastasis." (PMID 30197757, 2018). "In the tumor microenvironment, dominant and persistent STAT3 activity efficiently suppresses M1 macrophage polarization, dampening cytotoxic and proinflammatory functions including release of IL-12 and induction of Th1 antitumor immune responses." (PMID 29921770, 2018). "Given the role of the tumor microenvironment as a regulator of STAT3 activity, we tested the effect of the STAT3 inhibitor SH-4-54 on GBM migration and survival." (PMID 29566069, 2018). "As shown in a number of preclinical mouse tumor models and with emerging clinical data, tumor-mediated hijacking of myeloid cell function largely depends on the transcription factor, signal transducer and activator of transcription 3 (STAT3)." (PMID 29921770, 2018). "MDSCs from tumor-bearing mice have greatly increased levels of phosphorylated STAT3 compared with IMCs from naive mice, probably by upregulating the expression of STAT3 target genes, including B-cell lymphoma XL (BCL-XL), Myc, cyclin D1, and survivin." (PMID 29765990, 2018). "We also noticed that that OP-D substantially suppressed STAT3 phosphorylation and Li-67 in tumor tissues by immunohistochemistry." (PMID 30413072, 2018). "The immunohistochemical staining results of IL-6, p-STAT3 and NF-κB showed that the expression of these three proteins were significantly reduced in mouse tumor tissue sections of the Res group." (PMID 29390972, 2018). "The HT-L1 and HT-L2 metastatic sublines displayed higher levels of STAT3 Y705 phosphorylation and lower levels of acetylated tubulin than the HT-S1 and HT-S2 primary tumor sublines." (PMID 30209389, 2018).
tumor (continued). "The crosstalk between tumor cells and their surrounding extracellular signals forms tumor microenvironment and leads to activation of oncogenic signaling pathways, including STAT3 signaling pathway." (PMID 29717134, 2018). "This increased expression of phosphorylated STAT3 was maintained even after 18 days of tumor implantation." (PMID 30555329, 2018). "Stat3 is activated by mutant EGFR and JAK, and notably, pStat3 is associated with tumor cell proliferation and angiogenesis." (PMID 30174790, 2018). "Constitutively active STAT3 has been established to trigger deregulated gene transcription where the gene products consequently promote tumor progression." (PMID 30217007, 2018). "As a consequence, to achieve clinical efficacy, the conception and testing of anti-STAT3 targeted therapies will need a very careful evaluation of these opposing roles and of the most appropriate tumor context, disease stage and patient population to treat." (PMID 30231553, 2018). "In contrast, STAT3 knockdown in Monos reduced IL-10-induced PD-L1 protein expression, and p65 knockdown in tumor lines reduced IL-1a-induced PD-L1 expression." (PMID 30400822, 2018). "CT exerted its anti‐tumor effect by targeting STAT3/SIRT3/HIF‐1α signaling pathway in vitro and in vivo." (PMID 30094960, 2018). "Although numbers of STAT3‐expressing tumor cells were unchanged, we found increased STAT3 activation in STAT1∆IEC tumors." (PMID 29419930, 2018). "Constitutive activation of signal transducer and activator of transcription 3 (STAT3) in human tumors is associated, among others, with promotion of tumor cell EMT, migration, invasion, angiogenesis, and resistance to apoptosis." (PMID 30149591, 2018). "Here, we showed that the expression levels of STAT3 phosphorylation were higher in WT mice than PLCγ1 conditional knockout mice, leading to much higher tumor proliferation and inflammatory responses in the WT mice." (PMID 29464031, 2018). "Knockdown of STAT3 by siRNA or STAT inactivation with inhibitor in A549 cells significantly decreased tumor invasive and migratory activities in transwells and inhibited the formation of spheroids." (PMID 30013043, 2018). "Tumor-induced STAT3 plays a central role in regulating both the differentiation and tolerogenic effects of MDSCs." (PMID 29921770, 2018). "Constitutively active STAT3 signaling promotes tumor growth by upregulation of genes involved in cell survival." (PMID 30420593, 2018). "Local TAFs in breast cancers act as a paracrine source of the elevated IL-6, driving STAT3 activation and ERα-positive tumor cell proliferation both in vitro and in vivo." (PMID 29463044, 2018). "As shown by immunohistochemistry data, phosphorylation levels of STAT3 at Tyr705 in tumor tissues were substantially decreased after EAEO treatment." (PMID 29867489, 2018). "The authors attribute the augmentation of STAT3 activity in the tumour cells to the secretion of IL-6 and soluble IL-6Rα by the MDSCs." (PMID 29875329, 2018). "We further showed that the function of SIRT2 in tumour angiogenesis was dependent on the STAT3/VEGFA signalling pathway in CRC cells." (PMID 30584257, 2018). "To investigate the role of STAT3 in GBM tumor progression, we examined the effect of Dox-inducible STAT3-KD on GIC tumorigenicity in NSG mice." (PMID 29774125, 2018). "It has been also demonstrated that down-regulation or inhibition of STAT3 signaling can suppress tumor growth in vitro and in animal models." (PMID 30518397, 2018). "The unregulated activation of STAT3 has been demonstrated to occur in many cancers and enhances tumour growth, migration, and invasion." (PMID 30261753, 2018). "The efficient inhibition of STATTIC on activation of STAT3 pathway by tumor CM was testified before the experiment, and the experiment data showed that STATTIC‐treated tumor‐driven like macrophages decreased expression of IL‐8 in both mRNA and protein level." (PMID 30311406, 2018).
tumor (continued). "STAT3 is an oncogenic transcription factor and its aberrant activation has been involved in not only oncogenesis, but also tumor metastasis and EMT." (PMID 29547514, 2018). "In summary, we have identified a novel regulatory axis that IL-8/STAT3/MALAT1 in the effort of elucidating the tumor-promoting the function of M2 macrophages." (PMID 30591689, 2018). "The hepatocyte-Tim-3 receptor activates NF-kappa B phosphorylation, which in turn stimulates IL-6 secretion and STAT3 phosphorylation, resulting in tumor growth both in vitro and in vivo." (PMID 30175384, 2018). "PTPRT can function as a tumor suppressor through its interaction with its substrates, paxillin and STAT3." (PMID 30208623, 2018). "The upregulation of CD45 tyrosine phosphatase activity in MDSCs exposed to hypoxia in a tumor site was responsible for the downregulation of STAT3, and STAT3 has a unique function in the tumor environment in controlling the differentiation of MDSCs into TAM." (PMID 29765990, 2018). "MDSC isolated from mouse tumours displayed activated Stat3 and induced angiogenesis in an in vitro tube formation assay via Stat3 induction of angiogenic factors, including VEGF." (PMID 30537999, 2018). "For example, STAT3 phosphorylation, and therefore activation, in macrophages is commonly observed in the tumor microenvironment." (PMID 29867925, 2018). "Aloin was found to inhibit tumor angiogenesis and growth by signal transducer and activator of transcription 3 (STAT3) activation." (PMID 30235891, 2018). "A number of studies reported that constituent activation of Stat3 promotes inflammation and tumor growth by expanding MDSCs population by upregulating Stat3 target genes like B-cell lymphoma XL(BCL-XL), cyclin D1, Myc, and survivin." (PMID 30555467, 2018). "Consistently, a peptide fragment in the DP2 domain of STIP1 (peptide 520) disrupted the interaction between STIP1 and HSP90, thus affecting STAT3 signaling and leading to tumor growth inhibition in vitro and in vivo." (PMID 29914167, 2018). "Instead, a higher activation of STAT3 and STAT6 signaling promotes the accumulation of tumor-associated macrophages (TAMs) with strong immunosuppressive and proangiogenic potential." (PMID 29921770, 2018). "The analyses of primary tumor cells from patients with MM and established MM cells have consistently revealed that STAT3 is constitutively active in approximately 40–60% of MM tumors." (PMID 29899697, 2018). "In a gefitinib-resistant NSCLC model, HHT induced anti-tumor effects by suppressing interleukin-6 (IL-6)/JAK1/STAT3 signaling." (PMID 29844447, 2018). "Our research group has reported extensively on the role of TC-PTP in the regulation of STAT3 signaling in skin carcinogenesis." (PMID 30208623, 2018). "On the contrary, decreased STAT3 signaling caused an augment in STAT1 expression and reduced tumor growth." (PMID 30235866, 2018). "Meanwhile, LMP1 downregulates miR-204, which functions as a tumor suppressor by activating STAT3 to promote EBV-positive C666-1 cell invasion and metastasis." (PMID 32201498, 2018). "Although the crucial role of STAT3 in both tumour cells and the tumour microenvironment is evident, gaps remain in our understanding of the regulation of STAT3 signalling in cancer." (PMID 29630659, 2018). "The significance of RKIP-mediated STAT3 regulation on tumor survival has been also highlighted by other studies." (PMID 30149591, 2018). "For example, the tumor-promoting functions of NF-κB, STAT3, and AP-1 are correlated to expression of genes that stimulate cancer cell proliferation and survival." (PMID 29695779, 2018). "Inhibition of STAT3 using JAK inhibitor AZD1480 also found to decline tumour-associated myeloid population and inhibit myeloid infiltration to tumour site." (PMID 29455663, 2018). "In male lactotroph tumors, while we found STAP2 to be increased at all tumor grades, we noted that STAT3 and STAT5 were higher in male grade 2b/3 than in female grade 2b tumors." (PMID 30555413, 2018).
tumor (continued). "We previously showed that STAT3 is phosphorylated at Y705 in GICs isolated from the GBM6, GBMX10, GBMX16 and GBMX39 PDXs, and that the JAK tyrosine kinase inhibitor WP1066 blocks Y705-STAT3 phosphorylation and inhibited subcutaneous tumor growth by GBM6 GICs." (PMID 29774125, 2018). "STAT-3 plays a significant role in regulation of genes involved in tumor cell proliferation, survival and invasion." (PMID 29464101, 2018). "Among transcription factors, NF-κB is known as an important endogenous tumor promoter while STAT3 can increase tumor capacity in evading immune system by inhibiting maturation of dendritic cells." (PMID 30060570, 2018). "Co-expression of NF-κB and STAT3 mediates transcription of inflammatory cytokine genes in tumor cells." (PMID 29707119, 2018). "In the present work, we also showed that TGF-βRII inhibition led to STAT3 S727 phosphorylation and increased gemcitabine resistance of the tumor cells suggesting the crucial role of STAT3 in both tumor and stromal cells." (PMID 30065235, 2018). "The expression of phosphorylated STAT3 in the gastrocnemius muscle was increased in tumor-bearing mice at 10 days after tumor implantation." (PMID 30555329, 2018). "STAT3 plays a crucial role in tumor immunosuppression, which enables tumor to evade immune surveillance." (PMID 29963254, 2018). "An autoregulatory loop between STAT3 and miR-17–92 was also characterized, suggesting an involvement of this cluster in the pathogenesis of this tumor." (PMID 30201877, 2018). "mRNA expression cytokine profiling and ELISA identified the IL‐8 secretion was increasing in tumor‐driven like macrophages, and STAT3 pathway was involved." (PMID 30311406, 2018). "Skeletal muscles of C26 tumor-bearing mice were used to elucidate the connection between the elevated IL6/STAT3 signaling, cancer cachexia, and muscle wasting." (PMID 30072615, 2018). "It was documented that EGF and its receptor EGFR are frequently overexpressed in many forms of RCC, and signaling cascade through EGF/EGFR/STAT3 play an important role in tumor cell growth and EMT in RCC33,35,46." (PMID 29717134, 2018). "Tumor-associated macrophages (TAMs) can also affect HCC tumor progression through NF-κB, STAT-3, and HIF-1 signaling." (PMID 29568237, 2018). "All above data showed that SOCS3 suppression and sustained activation of STAT3 occurred in e-MDSCs, which were correlated with tumor-derived IL-6." (PMID 30083161, 2018). "Such tumours are described as being more differentiated than those in which STAT3 alone is activated." (PMID 29875329, 2018). "In summary, these results elucidate that magnolin promotes autophagy and cell cycle arrest through LIF/Stat3/Mcl-1 pathway, which in turn prevents the tumor growth of CRC." (PMID 29899555, 2018). "As expected, WT-STAT3 expression in STAT3-KD GICs restored vibrant tumor growth in the mice, demonstrating that the difference in tumor growth was STAT3-dependent." (PMID 29774125, 2018). "Pharmacological agents such as curcumin, piperlongumine, icaritin and LLL12 which blocked STAT3 phosphorylation were reported to suppress primary MM cell viability and/or MM tumor growth in animal models." (PMID 29914181, 2018). "Many new drugs, such as DNA methyltransferase inhibitors, can promote tumor cell apoptosis, cell proliferation, angiogenesis, and distant metastasis by inhibiting the phosphorylation of STAT3." (PMID 30271456, 2018). "Our current data should accelerate clinical evaluation of Ponatinib in CRC (and other tumor types) due to its anti-STAT3 activity particularly selecting patients with high STAT3 activity." (PMID 30572654, 2018). "Transcription factor STAT3 is often constitutively activated in various human cancers and controls the expression of multiple genes involved in tumor initiation, growth, progression, and apoptosis." (PMID 30046347, 2018). "Unfortunately, limited research focused on the prognostic role of STAT3 tumor cell expression in different molecular subtypes." (PMID 29560131, 2018).